MMP9 (matrix metallopeptidase 9)
Diseases named in the same sentence as MMP9 in open-access papers (continued):
Sharing a sentence is not in itself a finding about the gene and the disease.
Cerebral ischemia (continued). "After cerebral ischemia, MMP-9 expression and activity are notably increased within 12–48 h post-insult." (PMID 39457496, 2024). "In order to describe the temporal pattern of MMP-9 following cerebral ischemia, we obtained brain tissue samples from animals that had undergone the focal Middle Cerebral Artery occlusion model (MCAO) and from those that had undergone sham surgery." (PMID 38255970, 2024). "In the present study, we showed that melatonin protected against post-ischemic MMP-9 activation following permanent focal cerebral ischemia in mice." (PMID 39457496, 2024). "Previous studies focused on the time-dependent increases in MMP-9 levels post-injury, demonstrated the changes between the 6 and 5 days after brain ischemia." (PMID 38255970, 2024). "Given the well-known association between the MMP9 pathway and BBB integrity, as well as its role in hemorrhagic transformation following cerebral ischemia, the expression of MMP9 and its colocalization with cerebral microvessels were investigated." (PMID 37627321, 2023). "In animal studies, the effectiveness of doxycycline and minocycline, derivatives of tetracycline, in inhibiting MMP-2 and MMP-9 in a rat model of cerebral ischemia was confirmed." (PMID 36835040, 2023). "According to a similar study, luteolin can reduce the size of cerebral infarction in rats following cerebral ischemia via inhibiting MMP9 expression." (PMID 37612462, 2023). "Minocycline, a semi-synthetic tetracycline with anti-inflammatory and anti-apoptotic properties, inhibits MMP-9 activity and has shown neuroprotection in cerebral ischemia and in other models of brain injury." (PMID 37240207, 2023). "Specifically, it is a stress-response gene whose expression is up-regulated in cerebral ischemia, trauma and meningiomas, and it up-regulates the expression of MMP-9, with enhanced BBB damage." (PMID 37240207, 2023). "The expression of MMP-9 is a well-established destructive mediator of BBB disruption in cerebral ischemia, and MMP-9 has been shown to degrade TJs proteins that make up the BBB, leading to edema formation." (PMID 36434369, 2023). "A large number of studies have also focused on finding ways to inhibit MMP-9 activity to reduce cerebral ischemia–reperfusion injury." (PMID 37483355, 2023). "A recent study proved that HBO-PC reduced the activity and tissue expression of brain MMP-9, and improved cell death after global brain ischemia." (PMID 36729260, 2023). "It is appealing to consider the involvement of pericytes in the breakdown of the endothelial basement membrane via the production of metalloproteinases during cardiac stress, as previously shown with the rapid production of MMP9 during brain ischemia." (PMID 37183820, 2023). "Neutrophils are involved in brain injury after cerebral ischemia by releasing proteases, including elastase, metalloproteinase (MMP9) and cathepsin G, as well as reactive oxygen species, nitrogen species and inflammatory IL-1β." (PMID 36818726, 2022). "But when cerebral ischemia occurs, local inflammatory reaction makes MMP-9 greatly expressed in ischemic tissue." (PMID 35399851, 2022). "After cerebral ischemia, the degranulation of neutrophils leads to the release of stored MMP9, which leads to the increase of blood MMP9 level." (PMID 34313877, 2022). "MMP expression levels are very low under normal conditions, but the levels of MMP2 and MMP9 increase significantly within hours of cerebral ischemia." (PMID 36061592, 2022). "There is a certain relationship between the expression level of MMP9 and the hemorrhagic transformation after cerebral ischemia, the expression level of MMP9 can predict the possibility of transforming into cerebral hemorrhage." (PMID 34313877, 2022). "Among them, the level of MMP-9 is directly related to the area of cerebral infarction and the hemorrhagic transformation after cerebral ischemia." (PMID 35462697, 2022).
Cerebral ischemia (continued). "It has been demonstrated that MMP9 knockout (MMP9KO) mice were protected against cerebral ischemia and traumatic brain injury, reportedly due to the prevention of MMP9 activity at the BBB." (PMID 34034683, 2021). "The results of network pharmacology suggest that catalpol is involved in the regulation of inflammation, vascular homeostasis, and vascular remodeling after cerebral ischemia, which is closely related to F2, MMP9, VEGF/KDR, and ALB." (PMID 33505489, 2021). "Several recent studies have found that MMP-9 is involved in the expressions of E-cadherin or occludin in cerebral ischemia–reperfusion injury, acute lung injury, and acute kidney injury." (PMID 34425812, 2021). "Previous report showed that MMP-9 is unusually expressed in brains suffering from cerebral ischemia injury and its enhance the brain injury and breakdown of BBB." (PMID 34795593, 2021). "Under the stimulation of cerebral ischemia and hypoxia, microglia and astrocytes produce part of MMP-9 under the guidance of inflammatory factors." (PMID 33727944, 2021). "It is found that the level of MMP9 in peripheral blood of patients with cerebral ischemia is higher than that of normal controls." (PMID 33505489, 2021). "In conclusion, miR-149-5p had a regulatory effect on S1PR2 of pericytes after acute cerebral ischemia reperfusion in rats and had a neuroprotective effect by regulating the expression levels of MMP9 and SODs." (PMID 34224319, 2021). "MMP-9 belongs to the subfamily of MMPs that play a key role in blood-brain barrier injury and inflammatory processes after cerebral ischemia." (PMID 34054530, 2021). "This is as opposed to infiltration of neutrophils, which have been described as a major source of MMP-9 in cerebral ischemia." (PMID 33505320, 2020). "Cyclooxygenase (COX)-2 and matrix metalloproteinase (MMP)-9 are two crucial mediators contributing to blood-brain barrier (BBB) damage during cerebral ischemia." (PMID 32973660, 2020). "Studies have found that XXMD can reduce blood-brain barrier (BBB) destruction and cerebral ischemia, the mechanism probably realized by inhibiting the expression of MMP-9 and so on." (PMID 33133212, 2020). "In a rat model of cerebral ischemia, preventing neutrophil infiltration reduced MMP-9 release in the brain." (PMID 32028265, 2020). "A significant upregulation of miR-21 and MMP-9 was observed in the rat hippocampus 24-h after cerebral ischemia; miR-21 is involved in the ERK-mediated upregulation of MMP-9 through calcium-dependent mechanism." (PMID 32937836, 2020). "OMS (0.01 or 0.1 μmol/kg per hour for seven days) reduced brain angiotensin II, MMP-2 and MMP-9 upregulation following brain ischemia." (PMID 32156050, 2020). "In this enzyme family, NOX4 is upregulated in pericytes in the penumbra after acute brain ischemia, increasing production of matrix metalloproteinase-9 (MMP-9), that induces plasma leakage focally at pericyte somata." (PMID 32635451, 2020). "Our results demonstrated that administration of VAC extract ameliorates the deleterious effects of cerebral ischemia by reducing the infarct volume and sensory-motor disorder as well as MMP-9 level and increasing the serum level of IL-10." (PMID 31807255, 2019). "The matrix metallopeptidase 9 (MMP9), when activated upon both cerebral ischemia and inflammation, can degrade collagen type IV in the endothelial basement membrane, leading to disruption of the BBB and allowing entry of peripheral immune cells into the brain." (PMID 31660990, 2019). "Matrix metalloproteinases (MMPs), the most important ECM‐degrading enzyme in vivo, plays an influential part in cerebral ischemia/reperfusion, especially when the expression and activity of matrix metalloproteinase‐9 (MMP‐9) increases in ischemic brain tissue." (PMID 31566928, 2019).
Cerebral ischemia (continued). "In particular, levels of activated MMP9 drastically increase during acute stage cerebral ischemia, which is pivotal in the cascade leading to neurovascular unit injury, especially deterioration of the blood-brain barrier." (PMID 30723388, 2019). "During cerebral ischemia/reperfusion, increased expression and activity of MMP‐9 is one of the vital mechanisms that destruct BBB, promote the formation of brain edema, and aggravate ischemic brain damage." (PMID 31566928, 2019). "Most important, our findings are consistent with the preclinical and clinical data showing that sulfonylurea antagonists reduce plasma MMP-9 levels and hemorrhagic transformation in cerebral ischemia." (PMID 29617457, 2018). "It is known that MMP-9 in particular is released from brain endothelial cells is involved in the neuronal cell death that occurs after cerebral ischemia." (PMID 27642277, 2016). "Previous studies have reported that MMP-9 activation is initiated as early as 4 h, which reaches the maximum level at 24 h and persists for at least 5 d after cerebral ischemia, whereas activated MMP-2 reaches the highest level 5 d after MCAo." (PMID 27703487, 2016). "In a rat cerebral ischemia model, treatments preventing neutrophil infiltration reduced MMP-9 released in the brain." (PMID 27561990, 2016). "In contrast, the inhibition of MMP-9 ameliorates brain edema and infarct volume following cerebral ischemia." (PMID 27642277, 2016). "Neuroprotection by MMP-9 inhibition or reduction in cerebral ischemia has been attempted in multiple studies during the last decade, using different strategies for MMP-9 inhibition." (PMID 27445688, 2016). "Changes in Hif-1a expression by the administration of either anti miR-335 or miR-335 mimic in cerebral ischemia were accompanied with the corresponding alteration of the downstream genes Angpt2, Bnip3, Mmp9, Pai1 and Vegfa." (PMID 26030758, 2015). "These temporal profiles of expression after cerebral ischemia suggest a role of MMP-9 in secondary tissue damage and that of MMP-2 in tissue repair." (PMID 26637168, 2015). "It has been reported that MMP-9 knockout mice are resistant to BBB disruption induced by focal cerebral ischemia and that this protection is mediated by reduced degradation of ZO-1." (PMID 26012470, 2015). "It has been reported that MMP-9 knockout mice are resistant to BBB disruption induced by transient focal cerebral ischemia." (PMID 25897666, 2015). "Because cerebral ischemia-induced BBB disruption was significantly attenuated in MMP9 knock-out mice, MMP9 is indicated as a key inducer of BBB disruption after brain insult." (PMID 25941935, 2015). "A pathological role of MMP-9 after cerebral ischemia and reperfusion is well-known and has been addressed in the beginning of this section." (PMID 25955565, 2015). "RT-PCR analysis indicated that TNF-α, IL-1, ICAM-1, and MMP-9 mRNA levels were elevated and suggested that NF-κB was activated by ROS produced during the 14-min global brain ischemia and 24-h reperfusion injury." (PMID 26230326, 2015). "Previous studies showed that matrix metallopeptidase 9 (MMP-9) expression was upregulated during brain ischemia and HO-1 overexpression attenuated retinal cellular damage by intense light exposure." (PMID 26161238, 2015). "Our work highlights the potential hemorrhagic risk in administering G-CSF in combination with tPA during the acute phase of cerebral ischemia, probably though vascular alterations mediated by the MMP-9 release from peripheral neutrophils." (PMID 24885160, 2014). "MMP-9 (Gelatinase B) is up-regulated in neurological injuries such as cerebral ischemia, BBB disruption, edema formation, and hemorrhagic transformation." (PMID 24397933, 2014). "Neutrophils contain high levels of metalloproteinases (MMPs), such as MMP-9, and other destructive proteolytic enzymes, normally prepared to fight microbes, and contribute to the proteolytic activity after brain ischemia." (PMID 25309322, 2014).
Cerebral ischemia (continued). "Normally, MMP-9 plays an important role in both animal models of cerebral ischemia and human stroke." (PMID 23344156, 2013). "Matrix metalloproteinase (MMP)-9 is up-regulated after cerebral ischemia and neuroinflammation and is actively involved in blood–brain barrier disruption." (PMID 23522154, 2013). "Downregulation of proinflammatory mediators - including MMP-9 - was found to reduce the cerebrovascular inflammatory response and late cerebral ischemia after experimental SAH." (PMID 23555845, 2013). "The intracerebral injection of TWEAK induces MMP-9 activation, and either genetic deficiency of Fn14, or treatment with Fn14-Fc decoy inhibits cerebral ischemia-induced MMP-9 activation." (PMID 24273541, 2013). "MMP-9 (gelatinase B) is significantly upregulated in animal models of cerebral ischemia, traumatic brain injury, and neuroinflammation." (PMID 23522154, 2013). "In line with previous studies, an increased level of MMP-9 immunoreactivity was noted in vehicle-treated brains at 24 hours after cerebral ischemia in our investigation." (PMID 22438957, 2012). "In our previous study we found that MMP-9 protein expression was increased in gpx-1−/− mice during cerebral ischemia-reperfusion injury." (PMID 22412999, 2012). "It has been reported that MMP-9 following cerebral ischemia is able to degrade the endothelial basal lamina and thereby increase the permeability of the BBB." (PMID 23259581, 2012). "Experiments using a mouse model have indicated that MMP9 was a main contributor to BBB disruption in focal cerebral ischemia, which substantiates it role in neuropathology." (PMID 23185624, 2012). "Blockade of MMP-9 activity by pharmacological inhibitors or gene knockout strategies provide protective effects against cerebral ischemia." (PMID 22643046, 2012). "Substantial evidence indicates that pathological MMP-9 activity after cerebral ischemia degrades components of the ECM and tight-junctions, thus contributing to microvessel and BBB leakage." (PMID 22587708, 2012). "Animal experiments have shown that QKL injection can promote endothelial nitric oxide synthase expression, reduce calcium overload, regulate matrix metallopeptidase 9 expression, and inhibit inflammation in the murine model of cerebral ischemia/reperfusion." (PMID 22536287, 2012). "In the wild type mice, cerebral ischemia and reperfusion led to remarkable Evans blue extravasation, significantly increased gp91phox and MMP-9 levels and decreased occludin levels in the ischemic brain tissue." (PMID 22146586, 2011). "A deleterious role for MMP-9 is indicated because MMP-9 knockout mice are protected against focal cerebral ischemia brain trauma and experimental encephalomyelitis." (PMID 22018032, 2011). "In accordance with these reported studies, here we found that MMP9 expression was increased significantly in the rat ischemic penumbra 24 h after reperfusion, thus confirming the induction of MMP9 by brain ischemia." (PMID 21541054, 2011). "Research conducted in murines recently, indicates that the major source of MMP-9 in cerebral ischemia is represented by bone-marrow derived cells." (PMID 21110846, 2010). "Accordingly, previous work has demonstrated that oxidative nitrosylation concomitant to cerebral ischemia activates at least MMP-9 and leads to neuronal death." (PMID 21151608, 2010). "It seems that MMP-2 and MMP-9 expression is decreased after minocycline administration in rats with induced cerebral ischemia." (PMID 21110846, 2010). "Blockade of MMP-9 activity by pharmacological inhibitors or gene knock-out strategies provides protective effects for the brain against cerebral ischemia." (PMID 21092323, 2010). "The expression of MMP-9 is elevated after cerebral ischemia which is involved in accelerating matrix degradation, disrupting the blood-brain barrier, increasing the infarct size and relating to hemorrhagic transformation." (PMID 20514206, 2009).
Cerebral ischemia (continued). "Some other drugs showed the potential protective effects on cerebral ischemia by downregulating the expression of MMP-9." (PMID 20514206, 2009). "The findings above suggest that the endogenous tPA or rtPA treatment, through the enhancement of MMP-9 expression, play an important role in hemorrhagic transformation after cerebral ischemia." (PMID 20514206, 2009). "Following cerebral ischemia, angiotensin II (venous infusion) increases cerebral edema and mortality by inducing MMP-9 expression in vascular smooth muscle cell through angiotensin type 1 (AT1) receptor and NF-κB pathways." (PMID 20514206, 2009). "For example, MMP-2 and MMP-9 are upregulated during cerebral ischemia, however their temporal regulation differs." (PMID 19497125, 2009). "MMP-9 co-localizes with activated resident microglia and infiltrating leukocytes in rodents subjected to cerebral ischemia, indicating a link between activated immune cells and MMP expression." (PMID 18694515, 2008). "Cerebral ischemia and reperfusion are known to induce large increases in MMP-9 protein and activity in the affected hemisphere and MMP-9 has been associated with hemorrhage formation in humans and experimental animals." (PMID 16078993, 2005). "Despite the fact that neutrophil depletion was essentially complete prior to the focal cerebral ischemia in our experiment, we detected an increase in gelatinolytic activity corresponding to 86–88 kDa MMP-9." (PMID 16078993, 2005). "As reported by other scholars, CAG has been shown to dramatically decrease BBB permeability and infarct volume following cerebral ischemia/reperfusion injury in rats, and it protects tight junction proteins from degradation by inhibiting MMP-9/2 activity, thereby maintaining BBB integrity." (PMID 39942654, 2025). "However, MMP-9 also participates in plasticity and recovery throughout the late phase of cerebral ischemia." (PMID 39850789, 2024). "Additionally, MMP‐9 level serves as a potential biomarker for the continuous presence of cerebral ischemia." (PMID 38379112, 2024). "Besides MMP‐2, MMP‐3, and MMP‐9, other MMPs such as MMP‐1, MMP‐7, MMP‐8, and MMP‐12 have also been implicated in cerebral ischemia–reperfusion injury, although their specific roles and mechanisms are still being investigated." (PMID 38379112, 2024). "The expression of the MMP-2 protein increased at 120 h of cerebral ischemia/reperfusion in rats, while the activation of MMP-9 expression increased significantly at 4 h of reperfusion, peaked at 24 h of reperfusion, and returned to normal at 120 h of reperfusion." (PMID 38927572, 2024). "Within 24 h of cerebral ischemia, Treg cells demonstrate the capacity to suppress MMP-9 production." (PMID 38737099, 2024). "Additionally, during the first 48 h, an increase in MMP-9 not only relates to the volume of brain ischemia but also correlates with the observed neurological deficits." (PMID 39599732, 2024). "MMP-2(gelatinase A) and MMP-9(gelatinase B) have been the focus of BBB studies in cerebral ischemia due to their ability to degrade the basement membrane due to their substrate specificity for the major components of the perivascular basement membrane, collagen IV, laminin, and fibronectin." (PMID 37483355, 2023). "MMP-9 is considered as the most involved in inflammatory response induced by cerebral ischemia." (PMID 36835040, 2023). "Moreover, in 2002, Science published the first article in the top ten cited, further proving the mechanism of MMPs in cerebral ischemia, MMP-9 can be activated by S-nitrosylation during cerebral ischemia, thus inducing neuron apoptosis." (PMID 37483355, 2023). "In summary, the increase in MMP9 following cerebral ischemia promotes BBB disruption, extracellular matrix remodeling, inflammation, impaired cerebrovascular regulation, and oxidative stress, which collectively contribute to the expansion of the ischemic area and the development of cerebral edema." (PMID 37927954, 2023).